NOTCH1 (notch receptor 1)
Diseases named in the same sentence as NOTCH1 in open-access papers (continued):
Sharing a sentence is not in itself a finding about the gene and the disease.
demyelinating disease (2 papers, 2017 to 2025). A broad group of disorders that affect the myelin sheaths that cover the neurons. "Another study showed that IL-17 stimulation induced Notch1 activation in OPCs and promoted Th17-mediated demyelinating disease." (PMID 40290135, 2025). "Here we report that IL-17 stimulation induces NOTCH1 activation in OPCs, contributing to Th17-mediated demyelinating disease." (PMID 28561022, 2017). "Taken together, these findings demonstrate critical crosstalk between the IL-17 and NOTCH1 pathway, regulating Th17-induced inflammatory and proliferative genes to promote demyelinating disease." (PMID 28561022, 2017). "Taken together, these findings demonstrated that IL-17-induced NICD1–Act1 nuclear translocation promoted inflammatory gene induction in OPCs that enhanced cell proliferation and interfered with OPC maturation, providing a new mechanism for the IL-17 and NOTCH1 pathways in demyelinating disease." (PMID 28561022, 2017). "In the present study, we report for the first time that IL-17 crosstalks with NOTCH1, a pathway that is known to promote OPC proliferation and suppress OPC differentiation, contributing to demyelinating disease." (PMID 28561022, 2017). "Future studies are required to carefully determine the relative importance of NOTCH1 canonical versus Th17-induced target genes in OPC proliferation/differentiation and consequent demyelinating disease." (PMID 28561022, 2017).
disc degeneration (2 papers, 2018 to 2025). "In severe disc degeneration, RCOR2, STAT3, NOTCH1, SP1, and SART1 expression were elevated, while PRIM1 and LYAR expression levels were significantly reduced." (PMID 40799650, 2025). "Our findings uncovered a vital protective role of CD24-positive NP cells against disc degeneration and revealed that HIF-1α-NOTCH1 pathway activation is essential for the maintenance of CD24-positive notochordal cells." (PMID 30598696, 2018).
dry eye (2 papers, 2013 to 2015). "Additional studies have also implicated Notch1 in clinical manifestation of ocular surface disease; in particular, a reduction of Notch1 expression was demonstrated in the conjunctival cells of patients with dry eyes." (PMID 23874882, 2013). "A recent report showed that members of the canonical Notch signaling pathway i.e., Notch1, Notch2, Notch3, Jagged1, Dll1, were significantly down-regulated in dry eye as compared to the non-dry eye conjunctival epithelia." (PMID 26818247, 2015). "Mice with conditional deletion of Notch1 did not demonstrate any evidence of dry eyes based on aqueous tear production and had normal conjunctival goblet cells." (PMID 23874882, 2013).
Duchenne muscular dystrophy (2 papers, 2010 to 2016). Duchenne muscular dystrophy (DMD) is a neuromuscular disease characterized by rapidly progressive muscle weakness and wasting due to degeneration of skeletal, smooth and cardiac muscle. "We next asked if myofiber-specific activation of Notch1 improves muscle pathology in mdx mice, a widely used model for Duchenne Muscular Dystrophy (DMD) in humans." (PMID 27644105, 2016).
eosinophilic esophagitis (2 papers, 2017 to 2023). Eosinophilic esophagitis (EoE) is a chronic, allergic disease of the esophagus characterized clinically by symptoms of esophageal dysfunction (including vomiting, dysphagia, feeding disorders, food impaction and abdominal pain) which persist after treatment with proton pump inhibitors (PPIs). "Potential influence of these factors upon Notch1-mediated cell fates warrants further investigation in SCC as well as squamous epithelia under eosinophilic esophagitis where EMT and Notch3 downregulation are implicated (P.M.C. and H.N., unpublished observation)." (PMID 29170450, 2017). "Higher expression of the NOTCH 1 intracellular domain (NICD) was previously shown in ESCC, compared to benign esophageal squamous epithelium and eosinophilic esophagitis." (PMID 37444412, 2023).
esophageal tumors (2 papers, 2019 to 2024). "Loss of functional Notch1 had minimal impact on the normal esophagus, suggesting NOTCH1 may be a potential target to reduce the growth of premalignant esophageal tumors." (PMID 38870403, 2024).
familial Alzheimer disease (2 papers, 2016 to 2021). A degenerative disease of the brain that causes gradual loss of memory, judgment, and the ability to function socially. "Some familial Alzheimer’s disease (FAD) mutations in Presenilins can affect Notch1 processing/activation." (PMID 27364742, 2016). "Here, we show that, overall, PS/γ-secretase similarly cleaves Notch1 N100, wild-type APP C99, and familial Alzheimer’s disease (FAD)-linked APP C99 mutants in Chinese hamster ovary (CHO) cells, which further supports the limited PS/γ-secretase substrate specificity." (PMID 34073182, 2021).
follicular thyroid cancer (2 papers, 2015 to 2019). "Additionally, Notch1 had lower expression in a cell strain of follicular thyroid carcinoma (FTC), and the proliferation of cells could be restrained after transfecting the two types of cells with a plasmid expressing the Notch1 intracellular domain." (PMID 30622441, 2019).
glomus tumour (2 papers, 2013 to 2023). "Furthermore, lentiviral transduction of miR-200s and miR-34s in patient-derived primary tympano-jugular paraganglioma cell cultures was associated with NOTCH1 downregulation and increased levels of markers of cell toxicity and cell death." (PMID 23955600, 2013). "Glomus tumours harbour driver events in NOTCH1, its paralogues and other cancer genes that functionally converge in aberrant Notch signalling." (PMID 37749094, 2023).
hearing loss (2 papers, 2013 to 2018). "However, associations between noise induced hearing loss and Notch1 SNPs and their functional significance in the Notch1 gene on NIHL have not yet been studied." (PMID 30217173, 2018).
Hyperkeratosis (2 papers, 2010 to 2025). Hyperkeratosis is a histopathological term defining a thickened stratum corneum and may be present in many different skin conditions, with many possible overlaps. "We demonstrate that skin-specific inactivation of Notch1 and Notch2 simultaneously, or RBP-J, induces the development of a severe form of atopic dermatitis (AD), characterized by acanthosis, spongiosis and hyperkeratosis, as well as a massive dermal infiltration of eosinophils and mast cells." (PMID 20174635, 2010).
hyperlipidemia (2 papers, 2021 to 2022). "The expressions of IGs are significantly modulated in 21 human EC transcriptomic datasets by various PAMPs/DAMPs including LPS, IFNs, Notch 1 siRNAs, oxPAPC, LPC, shear stress, hyperlipidemia and oxLDL." (PMID 34248940, 2021). "Building upon these benchmark data, we sought to explore the impact of prolonged hyperlipidemia as well as the effect colchicine-based therapy on a variety of atheroprotective (Klotho, HOXA5, NOTCH1, and OCT4) and proatherogenic (HIF1a, SOX2, BMP4, and NANOG) genes." (PMID 36362692, 2022).
hypopharyngeal squamous cell carcinoma (2 papers, 2019 to 2021). "In hypopharyngeal squamous cell carcinoma, expression of miR-140-5p suppressed cancer cell migration and invasion abilities by regulating ADAM10-mediated Notch1 signaling." (PMID 34884487, 2021). "MiR-140-5p was down-regulated in hypopharyngeal squamous cell carcinoma (HSCC) tissues and cell lines and restoration of miR-140-5p in HSCC cells repressed tumor cell invasion and migration via targeting ADAM10/Notch1 axis." (PMID 31762692, 2019).
IgA nephropathy (2 papers, 2023 to 2024). "In addition, the crosstalk between Notch1 and Toll-like receptor 4 (TLR4) signaling regulates the inflammatory response in IgA nephropathy, indicating the potential role of Notch1 pathway activation in podocyte inflammation." (PMID 39598328, 2024). "Some scholars found that the expressions of Notch1 and Jagged1 were significantly upregulated in the kidney tissues of IgA nephropathy, and Notch1, HEY1, and HES1 were significantly reduced after administration of the Notch1 pathway inhibitor DAPT, thereby alleviating RIF." (PMID 36793762, 2023).
Infantile hemangioma (2 papers, 2019 to 2023). "Infantile hemangioma endothelial cells (HemECs) express Notch1, Jagged, Hey1, and other molecules in the Notch pathway, suggesting that Notch pathway-related molecules play an important role in affecting vascular endothelial cell proliferation." (PMID 37565874, 2023).
intestinal tumors (2 papers, 2019). "Comparison of mouse intestinal tumors with CMSs revealed a NOTCH1-dependent positive correlation between the KPN transcriptome and CMS4, and a negative correlation with CMS2/3." (PMID 31526760, 2019).
keratinocyte carcinoma (2 papers, 2022 to 2025). A skin cancer arising from the keratin-producing cells of the epidermis.
lentivirus infection (2 papers, 2016 to 2024). Virus diseases caused by the Lentivirus genus. "The relative expressions of Notch1 mRNA after 96h lentivirus infection were 0.913 ± 0.035, 0.737 ± 0.062 and 0.133 ± 0.027 respectively." (PMID 27259477, 2016). "To determine whether the increased expression of p15 induced by ANXA1 knockdown was mediated by NICD signals, we constructed stable NICD over‐expression and Notch1 knockdown cell lines by lentivirus infection." (PMID 39447086, 2024). "The relative expressions of Notch1 mRNA in the following groups of blank group, negative control group and shRNA-Notch1 group after 72h lentivirus infection were 1.002 ± 0.042, 0.909 ± 0.041 and 0.251 ± 0.049 respectively." (PMID 27259477, 2016).
limb ischemia (2 papers, 2020 to 2021). A ischemia that involves the limb. "Next, we assessed the regulation of miR-24-3p, Notch-1, and Dll-1 in muscle-resident microvascular cells exposed to hypoxia in the setting of mouse limb ischemia." (PMID 32138369, 2020). "Of interest, in a mouse model of limb ischemia, endothelial overexpression of the active form of Notch1 prevents the miR-24-3p-mediated anti-angiogenic effect and, conversely, the inhibition of Notch enhances the anti-angiogenic effect of miR-24-3p, showing that Notch1 is a target of miR-24-3p." (PMID 34527667, 2021).
limb-girdle muscular dystrophy (2 papers, 2024 to 2025). Limb-girdle muscular dystrophy (LGMD) is a heterogeneous group of muscular dystrophies characterized by proximal weakness affecting the pelvic and shoulder girdles. "Mutations in protein O-glucosyltransferase 1 (POGLUT1) cause a recessive limb-girdle muscular dystrophy (LGMDR21) with reduced satellite cell number and NOTCH1 signaling in adult patient muscles and impaired myogenic capacity of patient-derived muscle progenitors." (PMID 40825068, 2025). "Mutations in protein O-glucosyltransferase 1 (POGLUT1) cause a recessive form of limb-girdle muscular dystrophy (LGMD-R21) associated with reduced satellite cell number and NOTCH1 signaling in adult patient muscles and impaired myogenic capacity of patient-derived muscle progenitors." (PMID 39651163, 2024).
malignant mesothelioma (2 papers, 2017 to 2021). A malignant neoplasm of the pleura or peritoneum, arising from mesothelial cells. "For example, Notch1 and Notch2 receptors work oppositely on the survival of malignant mesothelioma cells." (PMID 28416750, 2017).
marginal zone lymphoma (2 papers, 2019 to 2021). A usually indolent mature B-cell lymphoma, arising from the marginal zone of lymphoid tissues. "Previous study of marginal zone lymphoma showed NOTCH signaling alterations, and we detected frequent NOTCH1 (4/35 = 11%) and NOTCH2 mutations (2/35 = 6%)." (PMID 34203889, 2021).
metastatic cancer (2 papers, 2015 to 2016). A carcinoma which has spread from the original site of growth to another anatomic site. "Importantly, this effect was also appreciable in in vivo setting, where PlexinD1 overexpression promoted metastatic cancer cell extravasation independently of Notch1." (PMID 27749937, 2016).
mitral valve prolapse (2 papers, 2019 to 2025). A fairly common and often benign valvular heart disorder characterized by redundancy or hooding of mitral valve leaflets so that they prolapse into the left atrium, often causing mitral regurgitation. "The mitral valve prolapse appeared to be significantly influenced by both pathogenic and VUS rare variants in FBN1 and by NOTCH1 and TGFBR2 VUS." (PMID 31536524, 2019).
muscular dystrophies (2 papers, 2010 to 2022). "In line with studies showing that the inhibition of the TNF signaling pathway is beneficial in DMD, our findings elucidate a new mode of action of TNF in downregulating Notch-1 that may be relevant in muscular dystrophies." (PMID 20814569, 2010).
myeloproliferative neoplasm (2 papers, 2020 to 2023). A clonal hematopoietic stem cell disorder, characterized by proliferation in the bone marrow of one or more of the myeloid (i.e., granulocytic, erythroid, megakaryocytic, and mast cell) lineages. "By accelerating STAT3 phosphorylation and increasing NOTCH-1 signaling, loss-of-function variants in SH2B3 have been linked to the oncogenesis of myeloproliferative neoplasms (MPN), early T-ALL, Ph-like ALL, B-ALL, and non-malignant hematological disorders." (PMID 36834692, 2023). "Loss-of-function mutations in SH2B3 are reported to play an important role in the oncogenesis of myeloproliferative neoplasms (MPN), early T-ALL, Ph-like ALL, B-ALL and nonmalignant hematological diseases by accelerating STAT3 phosphorylation and increased NOTCH-1 signaling." (PMID 32085659, 2020).
myopia (2 papers, 2020 to 2025). "H3K18la activates the expression of Notch1 in the insulin signalling pathway, thereby forming a ‘glycolysis—H3K18la—Notch1’ axis that induces myopia." (PMID 40984037, 2025).
Oral Epithelial Dysplasia (2 papers, 2019 to 2026). "Our aim was to analyze the expression of NOTCH1, several stem cell markers, and selected microRNAs in preneoplastic lesion of the oral cavity, oral epithelial dysplasia (OAD)." (PMID 41752081, 2026).
pancreatitis (2 papers, 2012 to 2015). Inflammation of the pancreas. "Further, it remains to be determined how pancreatitis and Notch1 loss potentially synergize to promote oncogenic K-ras induced PanIN formation." (PMID 23284900, 2012). "In the caerulein-induced pancreatitis mouse model, the expression of the exocrine genes disappeared in pancreatic exocrine cells, while genes normally associated with Notch components, such as Notch1, Notch2, Hes1, Jag2, and a low level of Dll1 were induced." (PMID 26729103, 2015). "However, recent studies examining the effects of oncogenic K-ras activation and Notch1 deletion individually in response to caerulein-induced pancreatitis have provided mechanistic clues." (PMID 23284900, 2012). "For instance, when the pancreas is injured by pancreatitis, the exocrine acinar cells lose their differentiated characteristics and present acino-ductal metaplasia, which strongly upregulates the expression of the receptors Notch1 and 2 and the target genes Hes1, Hey1, and Hey2." (PMID 26729103, 2015).
papillary thyroid cancer (2 papers, 2019 to 2020). "Many studies have aimed to clarify the relationship between Notch1 signaling and papillary thyroid carcinoma (PTC), but the results have been inconsistent to date." (PMID 30622441, 2019).
paraganglioma (2 papers, 2013 to 2019). A benign or malignant neoplasm arising from paraganglia located along the sympathetic or parasympathetic nerves. "This immature, multipotent phenotype is supported by constitutive amplification of NOTCH signaling genes and by loss of the microRNA-200s and -34s, which control NOTCH1, ZEB1, and PDGFRA in head and neck paraganglioma cells." (PMID 30813557, 2019).
parasitic infection (2 papers, 2019 to 2023). "This indicates that Eg.ferritin activates the Notch1/Jagged1 signal and activates higher expression of Notch1, which plays a major role in DC maturation and active Th1 response in parasitic infections." (PMID 37274316, 2023). "Notch1/2 deletion in T cells resulted in decreased numbers of Tfh and IL-21 production in response to parasitic infection and hapten immunization, translating into impaired germinal centre formation and IgG1 production independently of Notch's effects on IL-4." (PMID 31690218, 2019). "For example, conditional deletion of Notch1 and Notch2 (but not either in isolation) in mouse CD4+ T cells conferred susceptibility to Leishmania infection, suggesting that Notch is essential to generate IFNγ-secreting cells to control the parasitic infection." (PMID 31690218, 2019).
penile cancer (2 papers, 2021). A primary or metastatic malignant neoplasm that affects the penis. "These shared findings between VSCC and penile cancer might open possibilities for the enrollment in trials exploring the role of NOTCH-1 mutations as predictors of response to PI3K/mTOR inhibitors." (PMID 34209172, 2021).
periodontitis (2 papers, 2021 to 2022). An acute or chronic inflammatory process that affects the tissues that surround and support the teeth. "Downregulation of Notch1 and Jagged1 was accompanied by loss of bone, suggesting that the Notch1 signaling pathway plays a key regulatory role in periodontitis and bone metabolism balance." (PMID 35280902, 2022).
peripheral T cell lymphomas (2 papers, 2013 to 2020). "We also found mutations in NOTCH1/NOTCH2 and JAK/STAT genes, previously reported to be mutated in peripheral T-cell lymphomas: NOTCH1 (16/71, 22%), NOTCH2 (14/71, 19%), JAK3 (5/71, 7%), and STAT6 (2/71, 3%)." (PMID 31028364, 2020). "NOTCH1 has an important role in regulating the differentiation and function of diverse peripheral T cell subsets, but its role in peripheral T cell lymphomas is largely unknown." (PMID 23825651, 2013).
prostatic intraepithelial neoplasia (2 papers, 2012 to 2016). "Notably, inactivation of Notch1 in Ptenpc−/− tumours induced a strong inhibition of tumour growth compared with age-matched Ptenpc−/− littermates as measured by decreased number of glands affected by high-grade prostatic intraepithelial neoplasia and invasive PCa." (PMID 27941799, 2016).
retinal diseases (2 papers, 2021 to 2023). "Recently, the therapeutic value of miR-137 has been reported in hypoxia-induced retinal diseases, through targeting the Notch1 signaling pathway." (PMID 33670982, 2021).
retinitis pigmentosa (2 papers, 2019 to 2023). Retinitis pigmentosa (RP) is an inherited retinal dystrophy leading to progressive loss of the photoreceptors and retinal pigment epithelium and resulting in blindness usually after several decades. "In our study, the JNK1–c-Jun–Notch1 axis influenced some transcriptional factors and three opsins, such as Crx and Rhodopsin, which are drug targets of retinitis pigmentosa." (PMID 31450635, 2019).
sarcopenia (2 papers, 2022 to 2024). Progressive decline in muscle mass due to aging which results in decreased functional capacity of muscles. "Sarcopenia was nominally associated (p < .05) with 12 tRNAs, 3 tRFs, and 6 piRNAs, with target genes linked to cell proliferation and differentiation such as Notch Receptor 1 (NOTCH1), DISC1 scaffold protein (DISC1), and GLI family zinc finger‐2 (GLI2)." (PMID 38294260, 2024).